MTOR (mechanistic target of rapamycin kinase)
Diseases named in the same sentence as MTOR in open-access papers (continued):
Sharing a sentence is not in itself a finding about the gene and the disease.
lupus (continued). "Activation of mTOR plays a role in lupus T cell signaling dysregulation." (PMID 33748165, 2021). "Indeed, a blockade of mTOR with N-acetylcysteine, Rapamycin and Sirolimus, another mTOR inhibitor, has shown promising results in both pre-clinical and clinical settings since the activity of mTOR has been found to be increased in lupus T cells." (PMID 32397669, 2020). "The predominance of TCRβ+CD138+ cells presenting with memory phenotype and the suppression of CD138-expression with rapamycin in MRL/Lpr mice suggest that mTOR mediated expansion of CD138-expressing memory T cells may be associated with lupus pathogenesis in MRL/Lpr mice as well as in SLE patients." (PMID 32849532, 2020). "CD4+ T cells from SLE patients and lupus-prone mice showed increased mTOR activation." (PMID 32528480, 2020). "Contrary to the established role of Kyn in immunosuppression, its accumulation in autoimmune patients as well as its activation of the mTOR pathway suggests that Kyn may be pro-inflammatory in lupus." (PMID 32849620, 2020). "Oxidative stress activated the mTOR pathway in lupus T cells." (PMID 31057561, 2019). "As previous study shown, NAC improved lupus disease activity by blocking mTOR in T cells." (PMID 31130958, 2019). "Since mTOR activation and glycolysis are tightly linked, it is likely that glycolysis contributes at least in part to the expansion of these CD8+ TEM cells, and their novel predictive value warrants further examination in lupus mice." (PMID 30348969, 2018). "Although resveratrol can inhibit mTOR pathway, further study should be performed on whether resveratrol relieves lupus injury via inhibiting mTOR-mediated Th17 cell expansion." (PMID 27597882, 2016). "Interestingly, the accumulation of mitochondria in lupus T cells is resistant to mTOR blockade by Rapa or NAC." (PMID 24404161, 2014). "Our findings implicate the mTOR pathway as a critical contributor to human lupus." (PMID 18980674, 2008). "Thus, the interaction between elevated mTOR and nitric oxide signaling in lupus might be cell-type specific." (PMID 39234308, 2024). "However, the precise mechanism of KYN-sensitive mTOR activation during T-cell development and lupus pathogenesis has been unknown." (PMID 38519468, 2024). "SLE pathogenesis is associated with enhanced generation of IFNα from lupus monocytes induced by augmented activation of STING pathway, and enhanced expression of STING and subsequent production of IFNα by monocytes were downregulated by the suppression of the mTOR pathway." (PMID 37781360, 2023). "Likewise, B cells in lupus-prone animals overexpressed PI3K/AKT/mTOR molecules." (PMID 35050162, 2022). "Given its role in inflammatory processes, mTOR inhibitors are being developed to treat autoimmune degenerative diseases, such as systemic lupus erythematosus (SLE), but also obesity, and to improve cardiovascular health." (PMID 35955882, 2022). "For example, inhibition of glycolysis, lipid synthesis, and mTOR signaling can control inflammation and alleviate disease activity in lupus mice and SLE patients." (PMID 35251009, 2022). "A previous study showed that TLR7/IFN-α-mTOR signaling was significantly activated in total MDSCs in mice with early-aged lupus, suggesting that the abnormal differentiation of MDSCs might provide an important insight into the early diagnosis and treatment of SLE." (PMID 34282122, 2021). "A previous study showed that mTOR is activated in SLE, and subsequently enhances expression of Rab4, a small GTPase, in lupus T cells." (PMID 32903665, 2020). "The is also evidence that bisphenol A inducesthe development of systemic lupus erythematosus in MRL/lpr mice, atypical autoimmune disease, which is related to the up-regulation of the PI3K/AKT/mTOR signalling pathway." (PMID 38582846, 2024). "In addition, increased NO in T-cells from lupus patients and mice contributes to the activation of mTOR and accumulation of mitochondria, promoting SLE disease activity." (PMID 39234308, 2024).
lupus (continued). "To investigate the mechanism by which C. cicadae alleviates renal fibrosis in mice with lupus, we examined the expression of factors in the PI3K/mTOR‐mediated autophagy pathway." (PMID 38270299, 2024). "Furthermore, lupus animal experiments have demonstrated that inducing HO-1 or inhibiting the phosphatidylinositol 3-kinase (PI3K)/mammalian target of the rapamycin (mTOR)-mediated pathway may potentially reduce RSI expression, leading to the amelioration of LN." (PMID 39456477, 2024). "Salmonella infection disrupts SIRT1/AMPK checkpoint control of mTOR to impair autophagy, and alterations of autophagy contribute to the progression of various autoimmune diseases, including systemic lupus erythematosus (SLE)." (PMID 38835801, 2024). "Rapamycin prevents LN development in lupus-prone mice and patients with SLE by inhibiting mTOR and enhancing auto phagosome formation and auto lysosomal degradation." (PMID 37894915, 2023). "In addition, the immunosuppressive effect of the mTOR inhibitor rapamycin is beneficial to patients with systemic autoimmune diseases, such as systemic lupus erythematosus (SLE), rheumatoid arthritis, and organ specific autoimmune diseases." (PMID 36890410, 2023). "And, mTOR pathway is activated in T cells in parenchymal organs in SLE patients and lupus prone mice." (PMID 36008635, 2022). "with consistency, suppressing mTOR activity by deletion of RAPTOR, an essential signal adaptor for mTORC1, blocks plasma cell differentiation in a mouse model of lupus." (PMID 35958572, 2022). "By disrupting the mTOR pathway and decreasing ROS levels, NAC displayed beneficial efficacy in disease activity of lupus patients." (PMID 35958572, 2022). "After 5 months, mice with lupus were treated with vehicle, AMPK agonist metformin, and mTOR inhibitors INK128 and rapamycin for another 2 months." (PMID 34282122, 2021). "Furthermore, studies reported mTOR-regulated metabolism as a therapeutic target to heal autoimmune diseases (systemic lupus erythematosus (SLE))." (PMID 33924101, 2021). "mTOR inhibition with rapamycin showed immunoregulatory effects in several autoimmune disorders, such as systemic lupus erythematosus (SLE), chronic immune thrombocytopenia (ITP), type 1 diabetes, experimental autoimmune encephalomyelitis (EAE), and Crohn’s disease." (PMID 34065644, 2021). "As P-AKT is known to regulate MTOR, this protein known to be closely related to the pathogenesis of SLE (MTORC1 is activated and MTORC2 reduced in human lupus), was also tested." (PMID 34744730, 2021). "This mitochondrial dysfunction was also described in a mouse model of systemic lupus erythematosus (SLE) and was associated with activation of the PI3K pathway and mammalian target of rapamycin (mTOR), a kinase that modulates cellular growth, proliferation, and apoptosis." (PMID 34912234, 2021). "In all, the percentage of M-MDSCs significantly increased in mice with pristane-induced lupus, and AMPK/mTOR signaling was included in the differentiation of M-MDSCs." (PMID 34282122, 2021). "Researches demonstrate that rapamycin reduces NLRP3 inflammasome activation by inhibiting the mTOR/NF-κB pathway in macrophages, and mTOR regulates NLRP3 inflammasome activation via reactive oxygen species in murine lupus." (PMID 33551822, 2020). "Moreover, rapamycin, the most potent mTOR inhibitor, was suggested as an add-on therapy in rheumatoid arthritis (RA) and systemic lupus erythematosus (SLE)." (PMID 32899806, 2020). "Rapamycin prevents the development of LN in lupus-prone mice and SLE patients by inhibiting mTOR and enhancing autophagosome formation and autolysosomal degradation." (PMID 32903665, 2020). "Several recent papers have investigated the signaling pathways activated in lupus BMSC and have identified several “druggable targets” including mTOR, JAK-STAT, and the Wnt/β-catenin pathway." (PMID 30637490, 2019). "In lupus patients, it was reported that NAC significantly reduced kynurenine, which also decreased mTOR signalling." (PMID 30545086, 2018).
lupus (continued). "For example, inflammatory T cells from systemic lupus erythematosus (SLE) patients have substantially elevated glycolytic and mitochondrial metabolism and mTOR activity, as compared to healthy controls." (PMID 30320109, 2018). "Activation of the mammalian target of rapamycin (mTOR) has recently emerged as a key sensor of MHP and mediator of enhanced Ca2+ flux in lupus T cells." (PMID 27597882, 2016). "Rab4A, a small GTPase overexpressed in T cells of patients with systemic lupus erythematosus (SLE), has been shown to activate mechanistic target of rapamycin (mTOR) signaling, which promotes proinflammatory T cell development and predisposes to nephritis in SLE." (PMID 40585226, 2025). "Although studies have shown that Cordyceps cicadae and its extracts can affect the PI3K/mTOR pathway and autophagy activity in renal tissue, the effects of these extracts on lupus‐induced renal fibrosis has not been determined." (PMID 38270299, 2024). "Indeed, mTOR signaling is enhanced in SLE, which subsequently inhibits autophagy and is considered to be a central mediator to lupus pathogenesis." (PMID 38690268, 2024). "Importantly, this study identifies Rab4A as a promoter of mTOR activation, ANA production, proteinuria, and GN during lupus pathogenesis in vivo." (PMID 38519468, 2024). "A recent study suggested that lupus patients with APS had higher activation of the mTOR pathway as compared to those lupus patients without APS." (PMID 37727166, 2023). "Also, rapamycin ameliorated signs of senescence in MSCs from patients with systemic lupus erythematosus (SLE) and enhanced the immunomodulatory potency of MSCs from MRL/lpr mice through inhibition of mTOR signaling pathways." (PMID 35986247, 2022). "Additionally, Treg cells effects appear to be significantly modulated in humans compared to mice, which may be explained by the fact that blocking mTOR with rapamycin can complete nephritis blocking in several lupus-susceptible strains without affecting Treg cells in mice." (PMID 35251009, 2022). "mTOR and HIF-1α play a critical role in regulating cell growth and proliferation (e.g., Th17 cells), which are related to the abnormal development of T cells in lupus mice and SLE patients." (PMID 34434237, 2021). "In our study, the lupus group exhibited significantly lower autophagy expression compared with the normal control group, and ADSC/miR-20a-ADSC treatment increased autophagy activity by inhibiting the miR-20a-related Akt/mTOR pathway." (PMID 34721589, 2021). "Next, the study showed that the AMPK agonist metformin and the mTOR inhibitors INK128 and rapamycin could reduce the percentage of M-MDSCs in mice with pristane-induced lupus and TLR7- and IFN-α-induced BM differentiation into MDSCs in vitro." (PMID 34282122, 2021). "Suppression of EZH2 expression in CD4+ T cells might be mediating at least some of the therapeutic effects observed with blocking mTOR activation and with glycolysis inhibitors in SLE and lupus-prone animal models." (PMID 32395334, 2020). "Also, inhibition of mTOR is shown to reduce the production of dnT cells and favors the expansion of therapeutic CD4+CD25+Foxp3+ Treg cells in lupus-prone mice and SLE patients." (PMID 32849532, 2020). "To test whether these pathways were also critical for CD138 expression on lupus T cells, we treated CD4+TCRβ+CD138- cells with rapamycin, a specific mTOR inhibitor, and assessed the increase in CD138 expression." (PMID 32849532, 2020). "Inhibition of the mammalian target of rapamycin (mTOR) pathway by sirolimus, a drug approved and in clinical use to prevent transplant rejection, has shown promising effects in lupus animal models as well as in patients with both antiphospholipid syndrome and SLE." (PMID 30787878, 2019).
lupus (continued). "Furthermore, and consistent with an important role for mTOR-driven inflammatory T cells in the pathogenesis of lupus, a recent phase 1/2 trial reported that rapamycin had a beneficial impact on clinical disease scores in a cohort of 43 SLE patients." (PMID 30320109, 2018). "Systemic lupus erythematosus (SLE) patients exhibit depletion of the intracellular antioxidant glutathione and downstream activation of the metabolic sensor, mechanistic target of rapamycin (mTOR)." (PMID 26366134, 2015). "In the context of the findings reported here, it is worth noting that steroid and cyclophosphamide, known to ameliorate lupus, directly impact some components of the mTOR pathway (data not shown)." (PMID 18980674, 2008). "In addition, increased mTOR activity has been observed in samples from both central and peripheral regions of livedo reticularis skin lesions in aPL-positive systemic lupus erythematosus (SLE) and aPL-positive non-SLE patients." (PMID 40141392, 2025). "Signaling by the PI3K/Akt/mTOR pathway profoundly affects mRNA translation through phosphorylation of downstream targets such as 4E-BP and RPS6KB1; we further explored the level of phosphorylation of 4E-BP1 and RPS6KB1 in lymphocytes of mouse models of lupus with IGFBP2 blockade treatment." (PMID 36008635, 2022). "We also detected the expression of p-AMPK, p-mTOR and IRF-8 in kidney in pristane-induced lupus mice and found that IRF-8 and mTOR were highly expressed in the kidney tissues of SLE mice, and INK128 and metformin could significantly inhibit the expression of IRF-8 and the phosphorylation of mTOR." (PMID 34282122, 2021). "Thus, up to 2.4 g/day, NAC supplementation appears to be an effective therapeutic approach to lupus through increases in glutathione and subsequent inhibition of mTOR and restoration of double-negative T cell function and Treg count." (PMID 34239993, 2021). "Moreover, both AMP-activated protein kinase (AMPK) agonist metformin and two mammalian targets of rapamycin (mTOR) inhibitors (INK128 and rapamycin) inhibited the percentage of M-MDSCs in lupus mice as well as in the TLR7- and IFN-α-induced bone marrow (BM) differentiation into MDSCs in vitro." (PMID 34282122, 2021). "Similarly, in lupus-prone mice, B cells hyperexpressed PI3K/AKT/mTOR molecules." (PMID 34650560, 2021). "As recently revealed in comprehensive metabolome analyses of systemic lupus erythematosus (SLE) patients, NAC blocked mechanistic target of rapamycin (mTOR) activation." (PMID 30243020, 2018). "Therefore, we examined whether the metabolites that were found to be accumulated in lupus PBL and regulated by treatment with NAC (Kyn, HCA, and cAMP), were actually capable of activating mTOR." (PMID 26366134, 2015). "Studies have shown that the PI3K/AKT/mTOR pathway is crucial in a variety of inflammatory diseases such as chronic obstructive pulmonary disease (COPD), inflammatory bowel disease (IBD), multiple sclerosis (MS), and systemic lupus erythematosus (SLE), etc.." (PMID 35887375, 2022).
oral cancer (108 papers, 2015 to 2025). "In the present study, we demonstrated that the inhibition of mTOR signaling via rapamycin caused antitumor effects in a mouse model of oral cancer." (PMID 38791040, 2024). "Elevated p-mTOR expression was associated with cancer relapse and poor prognosis among oral cancer patients." (PMID 38560690, 2024). "Scarce information exists on the role of mTOR pathway proteins and their association to aggressiveness and prognosis of patients with canine oral cancers." (PMID 35883491, 2022). "The stated threats for oral cancer such as cigarettes, alcohol and human PV have also been reported to cause initiation of the Akt/mTOR pathway." (PMID 35251696, 2022). "LQ inhibited the progression of oral cancer through inducing autophagy-associated apoptosis via PI3K/AKT/mTOR pathway inhibition, revealing a new possible scheme for the treatment of oral cancer." (PMID 34488535, 2021). "It has been pointed out that the neutrophil gelatinase-associated lipocalin (NGAL) knockdown induced mTOR activation and, consequently, suppressed autophagy, thereby sustaining oral cancer progression." (PMID 33297472, 2020). "MAPKAP1, TSC1 and RPTOR are also involved in mTOR signaling, which has been associated with tumor growth and immune regulation in the local microenvironment of oral cancers." (PMID 30308005, 2018). "Activation of the mTOR signaling pathway has been linked to decreased radiation responsiveness in human oral cancer, thus it limits efficacy of radiotherapy." (PMID 27031247, 2016). "Uesugi demonstrated that loss of miR-218 activated mTOR-Akt signaling pathway through direct targeting RICTOR in oral cancer." (PMID 26610476, 2015). "The mTOR (mammalian or mechanistic Target of Rapamycin) is linked with oral cancer." (PMID 34393439, 2021). "Taken together, our findings demonstrated that LQ inhibited the progression of oral cancer cells by inducing autophagy-associated cell apoptosis via the inactivation of PI3K/AKT/mTOR pathway, revealing a novel mechanism through which LQ acts as a natural drug in oral cancer treatment." (PMID 34488535, 2021). "Taken together, the given data suggest a key role of mortalin in the Akt/mTOR-driven continued proliferation of oral cancer cells by inhibiting apoptosis and autophagy." (PMID 40940957, 2025). "One of the most frequently upregulated signaling pathways in oral cancer is the PI3K/Akt/mTOR pathway, which regulates key cellular and metabolic processes in OSCC." (PMID 40137387, 2025). "Previous studies have shown that afatinib can target the EGFR/mTOR/Mcl-1 axis, inducing tumor cell apoptosis, and has the potential to become a treatment strategy for oral cancer." (PMID 40696350, 2025). "Afatinib, targeting the EGFR/mTOR/Mcl-1 axis, shows promise as a therapeutic strategy for oral cancer, especially in patients with high EGFR and Mcl-1 expressions." (PMID 38888847, 2025). "BEZ235, an inhibitor of PI3K/Akt/mTOR signaling and the cyclin D1/CDK-4 complex, was shown to cause synergistic radiosensitization in oral cancer cells." (PMID 40940957, 2025). "Activation of the Akt/mTOR pathway has been demonstrated as a major pathway involved in oral cancer, its lymph node metastasis, progression to advanced stages, chemoresistance, radioresistance, and poor survival outcomes." (PMID 40940957, 2025). "Genistein, found in soybeans, induces autophagy in oral cancer cells by regulating the AMPK/mTOR pathway, hence suppressing tumor development and metastasis." (PMID 39595208, 2024).